LIN28B-AS1 (LIN28B antisense RNA 1)
Synonyms: dJ439I14.1; C6orf220; LINC00577
Gene: Long non-coding RNA gene on chromosome 6 (104,864,464 to 104,941,450, reverse strand). Ensembl gene ENSG00000203809.
Diseases named in the same sentence as LIN28B-AS1 in open-access papers:
LIN28B-AS1 is named in the same sentence as 1 disease in open-access papers, as found by Europe PMC text mining. Sharing a sentence is not in itself a finding about the gene and the disease. The quoted sentences say what the papers report.
tumor (1 paper, 2020). "Expectably, LIN28B-AS1 was depleted in LIN28B-AS1 KO tumor tissues, where IGB2BP1-dependent mRNAs, including Gli1, Myc, and IGF2, were decreased." (PMID 32917856, 2020). "Therefore, LIN28B-AS1 KO inhibits HepG2 xenograft tumor growth in mice." (PMID 32917856, 2020).